BRAF (B-Raf proto-oncogene, serine/threonine kinase)
Diseases named in the same sentence as BRAF in open-access papers (continued):
Sharing a sentence is not in itself a finding about the gene and the disease.
cancer (continued). "Targeting the receptors upstream of Ras isoforms, such as EGFR, as well as its downstream effectors, such as BRAF, however, has proven to be a successful strategy to achieve positive clinical impacts in human cancer." (PMID 31712554, 2019). "We focused on BRAF K601E, as it is the most frequently reported in cancers among the non-V600 BRAF alterations that we identified, and has been previously reported to activate the ERK pathway." (PMID 31158244, 2019). "It has been reported that SSAs carry a high frequency of activating BRAF mutations (75-82%), which also seems to be a marker of MSI-H cancers." (PMID 30774654, 2019). "Taken together, these observations establish BRAF as a key driver gene that is often altered in many different cancers." (PMID 31426419, 2019). "As BRAF and RAS mutations, especially KRAS, broadly occur in cancers, it will be of interest to systematically analyze the relationship between UHRF1/DNMT1 expression and BRAF/RAS mutations." (PMID 30696879, 2019). "A prototypical example of this challenge is observed in cancers that carry alterations in the serine/threonine protein kinase BRAF." (PMID 31581557, 2019). "Taken together, these data support that LDR actively restores BRAF-dependent repression of thyroid iodine metabolizing genes in thyroid cells at the initiation phase of cancer progression." (PMID 30760304, 2019). "In this study, BRAF V600E, RET/PTC1 rearrangement, and TERT promoter mutations were found to be associated with aggressive cancers 65.7% of the time." (PMID 31623671, 2019). "Recently, immunotherapeutic approaches have also been considered as a component of the treatment of BRAF-mutant cancers." (PMID 31426419, 2019). "The frequency of these mutations is higher in right-sided tumors, without any significant difference between unselected CRC and KRAS/NRAS/BRAF wt carcinomas." (PMID 31226844, 2019). "These techniques revealed negative results as compared to IHC which was capable of identifying a small portion of BRAF V600E-expressing carcinoma cells." (PMID 31781475, 2019). "Later, cancer cells treated with BRAF inhibitor renders cancer cells addicted to the increased OxPhos19." (PMID 30356107, 2018). "This loss is not however limited to MSI-high cancers, but is also found in microsatellite stable (MSS) tumors with BRAF mutation and high-level CpG island methylator phenotype (CIMP), in other words, in cancers deriving from the so-called serrated pathway." (PMID 30257705, 2018). "Here, for the first time, we analyzed anti-BRAF activity of BBR and demonstrated that it targets BRAF as a part of its anti-cancer activities." (PMID 29565994, 2018). "Epidermal growth factor receptor (EGFR), anaplastic lymphoma kinase (ALK), v-raf murine sarcoma viral oncogene homolog B1 (BRAF), and c-ros oncogene 1 (ROS1) mutations are now used to guide specific anti-cancer therapies to improve patient outcomes." (PMID 30065223, 2018). "BRAF mutant/MSS cancers often display hypermethylation events (at 60%) compared to the infrequent occurrence in conventional pathway cancers (3%)." (PMID 30598662, 2018). "This dedicated analysis on BRAF mutant cancers only is aimed at improving characterization of the heterogeneity found within BRAF mutant cancers." (PMID 30598662, 2018). "The remaining SSADs and BRAF mutant traditional serrated adenomas (TSA) develop into microsatellite stable cancers with a poor prognosis." (PMID 29304767, 2018). "Remarkably, we found this type of mutation in BRAF, ERBB2, JAK2, and EGFR in cancer genomes, suggesting that the dimerization works as a principal mechanism to regulate the activity of these kinases." (PMID 29930381, 2018).
cancer (continued). "BRAF mutant/MSI cancers are the most well-characterized subgroup of the serrated pathway due to the consistent findings of several clinicopathological and molecular features." (PMID 30598662, 2018). "The unique oncogene duet of coexisting BRAF V600E and TERT promoter mutations is an important recent discovery in human cancer as a robust genetic background for the development of the most aggressive disease in several cancers." (PMID 29422527, 2018). "A study of almost 10,000 metastatic CRC that were sequenced with MSK-IMPACT showed that non-V600 BRAF mutations occurred in 2.2% of cases, the vast majority being found in MSS cancers, and accounted for 22% of all BRAF mutations." (PMID 30598662, 2018). "By suppressing ERK phosphorylation, AZ304 effectively inhibited a panel of human cancer cell lines with different BRAF and RAS genetic statuses." (PMID 29755114, 2018). "Although the overall occurrence of BRAF mutant/MSS cancers is only 7%, a disproportionately large number of deaths would result due to their aggressive nature and poor survival." (PMID 30598662, 2018). "Histologically, BRAF mutant/MSS cancers are similar to BRAF mutant/MSI cancers in terms of being mucinous and poorly differentiated." (PMID 30598662, 2018). "We show that BRAF and AXL oncogene overactivation in cancers is likely to be among the driving forces for the loss of RIPK3 during tumorigenesis and the consequent escape from necroptosis, as well as other RIPK3-driven processes." (PMID 30157175, 2018). "Mutational profiling for >150 mutations across commonly mutated cancer genes including RAS, PIK3CA, BRAF, and PTEN as well as treatment data, including receipt of a biologic agent, were collected." (PMID 29771009, 2018). "We performed cellular component ontology analysis of 55 gene partners for BRAF detected in human cancers and found 16 (29%) with the potential to locate to the nuclear compartment." (PMID 30603699, 2018). "The unique oncogene duet of coexisting BRAF V600E and TERT promoter mutations are widely found to be a robust genetic background promoting human cancer aggressiveness, but the mechanism is unclear." (PMID 29422527, 2018). "Due to the aggressive nature of advanced BRAF mutant cancer, 60% of patients with BRAF mutant advanced cancer are less likely to be able to receive second-line chemotherapy." (PMID 30598662, 2018). "Rare mutations in BRAF and microsatellite instability (MSI) have been reported in about 1–3% of patients with PDAC, and agents used in other cancers to target these have also shown some promise." (PMID 29329208, 2018). "There are 36 protein kinases in the Cancer Gene Census; seven of them (EGFR, ERBB2, BRAF, FLT3, PRKACA, LCK, and FGFR2) had enriched PTM/mutation domains in our study." (PMID 29695735, 2018). "Since BBR has cytotoxic effects, identifying new BRAF inhibitors with less cytotoxicity is of great importance to cancer treatment." (PMID 29565994, 2018). "This relationship is greatly affected by the Y35N point mutation, which results in cellular cancer transformation due to decreased RHEB Y35N-BRAF interaction and increased BRAF-CRAF dimerization." (PMID 29320991, 2018). "Overall, PIK3CA mutations have been associated with KRAS mutant, MGMT methylated, and CIMP cancers; however, PIK3CA mutations in the catalytic exon 20 hotspot were found predominantly in BRAF mutant/MSI cancers." (PMID 30598662, 2018).
cancer (continued). "The next highest proportion of BRAF mutant cancers (at 17%) were grouped with CMS4 which consists of MSS cancers with upregulation of genes involved in epithelial-to-mesenchymal transition (EMT) and worse survival rates." (PMID 30598662, 2018). "As observed in patients who relapsed after treatment, cancer cells are finally able to escape to anti-BRAF therapy and tumors have re-initiated growth in two mice." (PMID 29487283, 2018). "In comparison to MMR-proficient/BRAF WT tumors (70.1% CDX2), those with MMR-deficient/BRAFV600E-mutated cancers (29.3% CDX2) have a significantly reduced expression (p < 0.0001)." (PMID 30257705, 2018). "Recently, a phase I trial of the first in class ERK inhibitor, ulixertinib, resulted in anti-cancer effects in a variety of advanced BRAF mutant cancers, including CRC, which had previously failed MEK-ERK therapy." (PMID 30598662, 2018). "Then, a concentration dependent reduction of p-ERK was observed in cancer cell lines with both BRAF statuses." (PMID 29755114, 2018). "By contrast, the vast majority of SSA/Ps with cancer exhibited BRAF mutation and CIMP-high, while SMOC1 methylation was infrequent in both the SSA/P and cancer tissues." (PMID 29435136, 2018). "We discover BRAF and AXL as the first two oncogenes that can drive the loss of RIPK3 expression in cancer cells." (PMID 30157175, 2018). "BRAF mutant/MSS cancers have been found to have a comparably high rate of chromosomal instability (CIN) as BRAF wild-type cancers." (PMID 30598662, 2018). "We discovered multiple mosaic-activating variants in 4 genes of the RAS/MAPK pathway, KRAS, NRAS, BRAF, and MAP2K1, a pathway commonly activated in cancer and responsible for the germline RAS-opathies." (PMID 29461977, 2018). "Years of RAF targeting in V600E BRAF cancers has revealed that dual RAF/MEK targeting can produce better clinical outcomes." (PMID 29662630, 2018). "Studies have suggested that robust MAPK pathway suppression is required for response in BRAF V600E cancers and acquired resistance to BRAF inhibitor combinations involve reactivation of the MAPK pathway." (PMID 29193645, 2018). "A fundamental question remains unanswered, however, as to how this oncogene duet cooperates mechanistically, particularly with respect to how BRAF V600E is functionally linked to the mutant TERT, in cooperatively driving human cancer aggressiveness." (PMID 29422527, 2018). "We next investigated if the difference in distribution of full length versus N-terminally truncated BRAF also applied to mutant versions of BRAF that are detected in human cancers." (PMID 30603699, 2018). "This is true for targeted therapies using tyrosine kinase inhibitors for EGFR or BRAF mutant cancers, but is also an increasingly recognized problem for immunotherapies." (PMID 29192388, 2018). "In contrast, in a subgroup of 66 stage II MSS and BRAF wildtype patients, APC methylation was associated with worse cancer-specific survival (HR 2.63 95% CI 1.21–5.68)." (PMID 29564023, 2018). "Our results reveal a potential role of BRAF and AXL oncogenes in driving the loss of RIPK3 expression and escape from necroptosis in various cancers." (PMID 30157175, 2018). "BRAF mutant/MSS cancers have multiple genetic aberrations that are representative of typical changes associated with both serrated and conventional pathways." (PMID 30598662, 2018). "Several studies have reported that BRAF mutant cancers are more likely to metastasize to the peritoneum rather than the lung or liver." (PMID 30598662, 2018). "A meta-analysis of advanced BRAF mutant cancers treated with either cetuximab or panitumumab plus chemotherapy found that anti-EGFR therapy did not influence survival benefit compared to control regimens." (PMID 30598662, 2018). "Based on previous reports ATC cancer cells are positive for BRAF V600E (8505C, SW1746, OCUT1) or KRAS G12R (CAL62) oncogenic mutation." (PMID 29435119, 2018).
cancer (continued). "Each microdissected sample was also tested for cancer hotspot mutations on KRAS, BRAF and NRAS genes, and for the T790M EGFR resistanc e mutation, but no mutation was found." (PMID 29492209, 2018). "We trained a classifier for which we removed both of the BRAF-dominated cancer types (THCA and SKCM)." (PMID 29617658, 2018). "BRAF inhibitors (BRAFi) target selectively the BRAF V600E/K genetic alteration found in several cancers." (PMID 30429474, 2018). "Most remarkable, in colon cancer carrying a BRAF-V600E mutation, oncogenic K-RAS and N-RAS are common in relapsed cancers despite single or even combination treatments targeting RTK, Raf, and MEK11." (PMID 30446677, 2018). "About 50% of allmelanoma patients have activating somatic mutations in the activator loop involvingL597, T599, V600, and K601 switching proto-oncogene BRAF into a constitutivelyactive protein kinase and cancer driver." (PMID 29615030, 2018). "More than 29 kinds of kinase inhibitors have been developed to treat various cancers, including the BRAF inhibitors vemurafenib and dabrafenib of ERK signaling and the MEK (Mitogen-activated protein kinase kinase) inhibitor trametinib." (PMID 29866191, 2018). "In summary, AZ304, a novel dual BRAF inhibitor, exerts potent anti-proliferative effects on selected cancer cells independently of the BRAF genotype." (PMID 29755114, 2018). "Cultured cancer cells harboring mutations in KRAS and BRAF were shown to take up DHA via GLUT1 when incubated with mM concentrations of ascorbate, and this was associated with a loss of cell viability." (PMID 30018566, 2018). "Another study found that of the three subgroups, BRAF mutant/MSS cancers were the most likely to present at stage IV, of high grade, and more distally located than BRAF mutant/MSI cancers." (PMID 30598662, 2018). "ERK inhibitors have been found to resensitize BRAF mutant cancer cells that have acquired resistance to either BRAF or MEK inhibitors." (PMID 30598662, 2018). "Known and predicted targets of miR-125b reported in prior studies of cancers characterized by BRAF alterations include MLK3, KLF13, CXCL11, and FOXA1." (PMID 30131528, 2018). "ERK signaling is activated in more than 30% of human cancers, most frequently via RAS (rat sarcoma virus) and BRAF (v-Raf murine sarcoma viral oncogene homolog B) mutations." (PMID 29866191, 2018). "The majority of the BRAF mutant cancers (at 70%) grouped into CMS1 which was enriched with cancers positive for MSI, methylation, activated immune pathways, and a high propensity for females." (PMID 30598662, 2018). "It is possible that there are quantitative and qualitative differences in CIMP and interestingly less TSAs and BRAF mutant, mismatch repair proficient cancers met the definition of a high level of CIMP." (PMID 29304767, 2018). "Hierarchical clustering of different samples, based on their DNA methylation patterns showed that all samples containing the BRAF-V600E mutation (i.e. all SSPs, one TSA and one carcinoma sample) clustered together." (PMID 29590112, 2018). "CUP adenocarcinomas and poorly differentiated carcinomas harboured the highest frequency of variants in genes involved in signal transduction pathways (e.g. MET, EGFR, HRAS, KRAS, and BRAF)." (PMID 29973234, 2018). "This survey confirmed BRAF-V600E mutation in all SSP samples and also in one of the carcinoma samples and one of the TSA samples." (PMID 29590112, 2018). "The thorough analysis of the few cases with membrane staining (n = 12) revealed that all but one carcinoma were wild type for the studied mutations (NRAS, BRAF or TERTp)." (PMID 29298843, 2018). "Cancer-associated mutations in KRAS (10–30%), EGFR (10%) and BRAF (3%) in NSCLC patients are common." (PMID 28806950, 2017).
cancer (continued). "The incidences of all-grade and high-grade cuSCC in cancer patients treated with BRAF inhibitor were 12.5% (95% CI: 10.8–14.6%) and 11.6% (95% CI: 9.8–13.8%), and dual BRAF/MEK inhibitors were 3.0% (95% CI: 2.0–4.5%) and 2.8% (95% CI: 1.9–4.0%), respectively." (PMID 29137342, 2017). "In a pan-cancer analysis, we found that genomic aberrations in BRAF and VHL exhibit downstream effects that are clearly distinct from other genes." (PMID 29322935, 2017). "In contrast, low levels of DNA hypermethylation (CIMP-Low) were associated with left-sided cancers, a male predominance, KRAS mutation, BRAF wild type and MSS." (PMID 28097409, 2017). "BRAF testing was mostly performed directly by molecular cancer genetic platform in patients with KRAS wild-type CRC since the two mutations are mutually exclusive." (PMID 29137623, 2017). "Adaptation to BRAF inhibitors therefore represents a potentially valuable application of dynamical modeling to a rapidly moving field of cancer biology." (PMID 29175850, 2017). "The expression levels of BRAF-ref and BRAF-X1/X2 are inversely correlated, while the most prevalent among the three isoforms varies from cancer type to cancer type." (PMID 28454577, 2017). "In humans, BRAF is a gene found in cancer cells, it is critical, which is responsible for making a protein called BRaf, which is involved in the cells of human body, sending signals to activate the cell proliferation." (PMID 28303522, 2017). "Our meta-analysis demonstrated that the combination of BRAF and MEK inhibition, as compared with BRAF inhibition monotherapy, significantly decreased the incidence of secondary cancers." (PMID 28416755, 2017). "A recent study reported that SCH772984 inhibited the proliferation of RAS, or BRAF, mutant cancer cells." (PMID 28785594, 2017). "BRAF, a downstream target of RAS proteins, is a common target for activating mutations and fusions in diverse cancer forms including PA." (PMID 28448514, 2017). "This is consistent with our knowledge that, in this type of cancer, BRAF V600E recruits DNA methyltransferase to CGI targets by stimulating the MEK/ERK signaling pathway and upregulating the transcription repressor MAFG." (PMID 29125844, 2017). "These two pathways are frequently activated in cancer cells due to aberrant activation of RTKs and/or activating mutations in their downstream signaling molecules such as KRAS and BRAF." (PMID 28002807, 2017). "Several known cancer mutations were seen in unique samples (KRAS p.G12D, BRAF p.D594G, NF1 p.R1362*, and ZFAND1 p.R130*)." (PMID 28852190, 2017). "In cancer, RAS and BRAF are among the most frequently mutated members of this extracellular signal-regulated kinase pathway." (PMID 27965461, 2017). "This drug developed by small molecules with a significant property of BRAF inhibition, resulting in a reduction of cancer cell proliferation." (PMID 28303522, 2017). "As such, research focus has moved towards targeting downstream pathway components, such as MEK, in BRAF-mutant PLGGs and adult cancers." (PMID 29156677, 2017). "We found that miR-31 and miR-135b were significantly up-regulated, while, miR-193a-3p was marginally significantly down-regulated (P = 0.09) in BRAF-mutant cancers compared to KRAS-mutant cancers." (PMID 29115941, 2017). "Recent studies have revealed the benefits of combined targeted therapy with a RAF-inhibitor (Dabrafenib) and a MEK-inhibitor (Trametinib) in treating V600 BRAF mutant cancers, including NSCLC." (PMID 28947956, 2017).